CD68 (CD68 molecule)
Diseases named in the same sentence as CD68 in open-access papers (continued):
Sharing a sentence is not in itself a finding about the gene and the disease.
hilar cholangiocarcinoma (3 papers, 2015 to 2023). A cholangiocarcinoma that arises from the junction, or adjacent to the junction, of the right and left hepatic ducts. "In the present work we propose a well described and ubiquitous type of TAMs, in particular cells expressing CD68, as simple diagnostic tools prognosticating patient outcome in hilar cholangiocarcinoma." (PMID 26497197, 2015). "In contrast, an increased number of CD68+ macrophages was observed in patients with Klatskin tumors (D06-D08) as well as in one patient diagnosed with HCC (D09), indicating high macrophage activity." (PMID 33918803, 2021). "We analyzed surgically resected tumor specimens of hilar cholangiocarcinoma (n = 47) for distribution and localization of TAMs, as defined by expression of CD68." (PMID 26497197, 2015). "In conclusion, in the current study we demonstrate for the first time that presence of CD68-positive TAMs in tumor invasive front correlates with tumor recurrence and serves as an independent prognostic factor for survival in hilar cholangiocarcinoma." (PMID 26497197, 2015). "Analyzing immunoreactivity for CD68-positive TAMs in tumor samples from patients who underwent resection for hilar cholangiocarcinoma, we were able to show that." (PMID 26497197, 2015). "No multivariate analysis was conducted for perihilar cholangiocarcinoma as only tumor_CD68 was associated with lymph node metastases." (PMID 36980192, 2023). "Thus, reduced density of CD68 in TIF might mitigate tumor angiogenesis and improve survival in hilar cholangiocarcinoma." (PMID 26497197, 2015).
hypopharyngeal carcinoma (3 papers, 2016 to 2026). Carcinoma, predominantly squamous cell, arising from the epithelial cells of the hypopharynx. "In order to investigate whether AEG-1 expression was associated with MMP-9 expression in hypopharyngeal cancer, we performed immunohistochemical staining of AEG-1, CD68 and MMP-9 (key regulator of tumor invasion) in serial sections." (PMID 27793010, 2016). "In a tissue microarray cohort of 96 patients, CD68 + and CD163 + macrophages were more abundant in oral and oropharyngeal tumors compared to laryngeal and hypopharyngeal carcinomas (p = 0.001 and p = 0.06, respectively)." (PMID 41591510, 2026). "Again, hypopharyngeal cancers had the lowest number of infiltrating CD68+ and CD163+ macrophages in each compartment (CD68: p < 0.05 vs. oral cavity and CD163: p < 0.05 vs. larynx)." (PMID 39630300, 2024). "In marked contrast to the adjacent non-tumor tissue, tumor samples from hypopharyngeal cancer showed higher expression of AEG-1 in macrophages defined by CD68 (Cluster of differentiation 68, a macrophage marker) staining (Figure 1A5–1A12)." (PMID 27793010, 2016).
kidney stone (3 papers, 2018 to 2024). "Immunofluorescence for CD68 also showed a sizeable inflammatory cell infiltrate in the kidney with nephrolithiasis." (PMID 39457592, 2024). "In the present study, the significantly higher number of interstitial crystal deposits in the papilla of SFs and relatively high CD68 expression level in NSFs suggest some important roles of macrophages in kidney stone prevention." (PMID 29530009, 2018).
liposarcoma (3 papers, 2023 to 2025). A usually painless malignant tumor that arises from adipose tissue. "Other studies revealed that CD14+, CD68+, and CD163+ macrophages were associated with a poor OS in myxoid liposarcoma and dedifferentiated liposarcoma." (PMID 37958467, 2023). "Although most liposarcomas lacked substantial immune infiltration, CD20 and CD68 positivity clustered within PD-L1-high and CD8-rich cases, supporting the presence of a limited but biologically relevant immune-inflamed phenotype." (PMID 41296438, 2025).
liver failure (3 papers, 2014 to 2024). A liver disease characterized by the liver losing or has lost all of its function. "Intrahepatic EZH2+ cells were increased in the liver failure patients, some of them were closely related to CD68+ cells (Kupffer cells), accompanied with substantial increased infiltrating cells, compared to those from HC." (PMID 29789597, 2018).
lymphedema (3 papers, 2022 to 2025). Excess fluid collection in tissues, causing swelling. "It was reported that in mouse tail lymphedema model, VEGF-C was overexpressed by CD68+ cells, a macrophage marker, leading to the worsening of lymphedema’s most distinctive symptom, edema, and this was positively correlated with vascular leakage that initiated the fluid influx into the tissue." (PMID 36386144, 2022).
medulloblastoma (3 papers, 2022 to 2026). A malignant, invasive embryonal neoplasm arising from the cerebellum. "Different proportions of macrophages were found in the collected medulloblastoma tissues, and large amounts of CD68+HLA-DR+CD163+ cells were found." (PMID 40303994, 2025). "We obtained a total of 71 paraffin sections from patients with medulloblastoma, and detected the activated phenotype (M1/M2) by monoclonal antibodies for CD68, HLA-DR and CD163 with multiple fluorescence immunohistochemistry method." (PMID 35860588, 2022). "Myeloid-derived cells, as detected by CD68 expression, were in general increased in DIPG, ATRT, and medulloblastoma tumor samples compared to normal brain." (PMID 41541220, 2026).
metastatic melanoma (3 papers, 2018 to 2022). A melanoma that has spread from its primary site to another anatomic site. "Human primary and metastatic melanoma specimens exhibited increased infiltration of macrophages, as indicated by increased CD68-positive (yellowish-brown) granules in the cytoplasm and/or cell membrane compared with the normal pigmented nevus tissues." (PMID 30459241, 2018). "CD68 immunostaining can occur in 75% of metastatic malignant melanoma." (PMID 34449584, 2021).
monocytic leukemia (3 papers, 2015 to 2025). "Among them, HS and monocytic leukemia have some similarities in their IHC phenotypes, as both can express one or more monocytic neoplasm antigens, such as CD68, CD163 and lysozyme." (PMID 26187047, 2015). "Also, in a study, it was determined flow cytometrically that it has a differentiating effect on the high‐dose (10−3 M) MP human monocytic leukemia cell line U‐937 using terminal differentiation markers CD11b and CD68." (PMID 41438200, 2025). "The expression of CD68 is normally negative in BPDCNs, whereas a positive CD68 expression indicates that the BPDCN may be transformed into acute or chromic leukemia and particularly monocytic leukemia." (PMID 25780395, 2015).
Myeloma (3 papers, 2019 to 2025). "Myeloma cells were found closely associated with CD68-positive multinucleated osteoclasts." (PMID 30539276, 2019). "Besides dysfunctional CD8+ T-cells, tumor-associated macrophages (CD68+, CD163+, CD86−) and inactivated DCs (CD58−) are also found co-localized with myeloma cells, participating as well in the orchestration of an immunosuppressive state." (PMID 40227595, 2025).
myxoma (3 papers, 2015 to 2024). A benign soft tissue neoplasm characterized by the presence of spindle and stellate cells, lobulated growth pattern, and myxoid stroma formation. "Immunofluorescent examination with a cocktail of antibodies against spike SARS-CoV-2/CD34 and spike SARS-CoV-2/CD68 was performed in 2 cases out of 11 (proliferating myxoma and classic myxoma)." (PMID 37895467, 2023). "Utilizing antibodies against PDE3A, Ki67, CD3, CD8, CD68, and CD206, we employed multiplex immunohistochemical staining to investigate the composition of myxoma cells, T cells, and macrophages in each patient." (PMID 39090109, 2024). "Myxomas show a diffuse positive reaction for the immunohistochemical marker Vimentin and focal expression of CD34, CD68, and SMA." (PMID 26509093, 2015).
neuropathy (3 papers, 2019 to 2024). A disorder affecting the nervous system that manifests with pain, tingling, numbness, and/or muscle weakness. "Previous studies reported that in the CCI-induced neuropathy model, the TNF-α, IL-1β signals, and infiltration of CD68+ inflammatory cells induced a partial decrease after nerve release." (PMID 35893792, 2022).
non-alcoholic steatohepatitis (3 papers, 2021 to 2022). "Interestingly, particularly in the NASH condition, agglomerates of CD68-positive cells form ring structures around degenerated hepatocytes, also known as hepatic crown-like structures (hCLS), which has been described as a histopathological feature in non-alcoholic steatohepatitis in mice and human." (PMID 34668024, 2022).
non-Hodgkin lymphoma (3 papers, 2025). Distinct from Hodgkin lymphoma both morphologically and biologically, non-Hodgkin lymphoma (NHL) is characterized by the absence of Reed-Sternberg cells, can occur at any age, and usually presents as a localized or generalized lymphadenopathy associated with fever and weight loss. "Immunohistochemistry (IHC) is essential for accurate diagnosis, with MPO, lysozyme, and CD68 confirming myeloid lineage and excluding mimickers such as high-grade non-Hodgkin lymphomas." (PMID 40951125, 2025). "HS is diagnosed using positive immunohistochemistry for histiocytic markers, such as CD68, CD4, CD163, or lysozyme, and can present in an isolated form or be associated with other hematologic malignancies, such as non-Hodgkin lymphoma (NHL) or acute leukemia." (PMID 40066099, 2025). "In non-Hodgkin lymphoma, while CD68-positive content has been correlated with improved survival, an increased CD163/CD68 ratio predicts worse prognosis." (PMID 41239536, 2025).
pancreatic adenocarcinoma (3 papers, 2015 to 2022). "A recent report on homotypic cell cannibalism in pancreatic adenocarcinoma suggested ectopic expression of the scavenger receptor gene CD68 as a marker of cannibalistic cells in pancreatic adenocarcinoma." (PMID 26504802, 2015).
papillary thyroid cancer (3 papers, 2014 to 2025). "In contrast, some studies have indicated that low CD68 levels are associated with shorter survival, like in papillary thyroid cancer." (PMID 38357542, 2024). "In thyroid tumors, the number of CD68+ TAMs is also higher in papillary carcinoma than in follicular adenomas." (PMID 25499804, 2014). "Although the Medians of CD68+ and CD163+ cells in the TC group were almost similar, the balance of M1 and M2 macrophages varied significantly inside the group, so the CD68/CD163 ratio was low in patients with papillary thyroid carcinoma, comprising 0.563 (0.082–3.0)." (PMID 39936166, 2025).
Peri-Implantitis (3 papers, 2021 to 2023). An inflammatory process with loss of supporting bone in the tissues surrounding functioning DENTAL IMPLANTS. "An analysis of grafted peri-implantitis connective tissues showed the expression of CD68, MPO and iNOS surface proteins." (PMID 37232785, 2023). "According to peri-implantitis severity classification, slight (n = 6), moderate (n = 6), and advanced (n = 6) cases revealed CD68 expression mean values of 13% (95% CI 7–19), 15.8% (95% CI 10.9–20.8), and 12.8% (95% CI 11–14.8), respectively." (PMID 32886246, 2021). "In addition, Carcuac and Berglundh evidenced in an immunohistochemical analysis of 40 peri-implantitis soft tissue specimens that positive cells for CD68 marker occupied 11% of the total ICT area (3.48 ± 2.54 mm2)." (PMID 32886246, 2021).
periodontal disease (3 papers, 2021 to 2023). "We also calculated the total number of identified cells (CD66b+, CD4+, CD8+, CD56+, CD68+, Siglec8+, CD138+) and OSCC patients showed significantly more cells (55,966 ± 22,151) compared to periodontal disease (32,550 ± 11,816) and control patients (6,355 ± 4,733)." (PMID 35048057, 2021).
sarcomatoid carcinoma (3 papers, 2009 to 2018). A malignant epithelial neoplasm characterized by the presence of spindle cells and anaplastic morphologic features. "As other immunohistochemical markers were negative, including CD45, CD163, CD68, Desmin, Myogenin, Melanoma, S100, α-SMA, Cytokeratin 7, Cytokeratin 20, MDM2 and CDK4, the tumors were diagnosed as sarcomatoid carcinomas." (PMID 29874846, 2018).
schistosomiasis (3 papers, 2016 to 2023). An infectious disease caused by parasitic trematodes of the genus Schistosoma that colonize human blood vessels and release eggs that can cause granulomatous reactions leading to acute (swimmer's itch or acute schistosomiasis syndrome) or chronic disease. "In the liver pathology of schistosomiasis, Gm26917 was also found to colocalize predominantly with CD68-positive macrophages." (PMID 36386180, 2022). "Double immunohistochemistry for OPN and CD68 (a macrophage marker) confirmed that the macrophages in acute schistosomiasis express this pro-inflammatory cytokine." (PMID 27755536, 2016).
Seizure (3 papers, 2018 to 2022). A seizure is an intermittent abnormality of nervous system physiology characterized by a transient occurrence of signs and/or symptoms due to abnormal excessive or synchronous neuronal activity in the brain. "Changes in MHCII and CD68 are also well-documented after epileptic seizures and SE." (PMID 31333561, 2019).
subarachnoid hemorrhage (3 papers, 2019 to 2023). A serious neurological disorder characterized by intracranial hemorrhage into the subarachnoid space. "Subarachnoid hemorrhage resulted in an increase in the number of Iba‐1‐positive and CD68‐positive epiplexus cells on the choroid plexus, as well as an increase in soma size in Iba‐1‐positive cells." (PMID 31433571, 2019).
synovial sarcoma (3 papers, 2019 to 2024). "Significant differences were observed in CD8 and CD56 expression in LMS, and CD68 expression in synovial sarcoma (p = 0.003, p = 0.03 and p = 0.03, respectively)." (PMID 38291183, 2024). "When evaluating synovial sarcoma samples, the most prevalent immune marker was CD68/CD163." (PMID 35267598, 2022). "Synovial sarcomas had lower CD68 staining when compared with all other diagnoses." (PMID 30999901, 2019).
synucleinopathy (3 papers, 2018 to 2024). A neurodegenerative disease that is characterized by the abnormal accumulation of aggregates of alpha-synuclein protein in neurons, nerve fibers or glial cells. "Our data show that such a loss in Iba1 and CD68 proteins is also evident in the A53T model of synucleinopathy, suggesting a common theme in microglial responses in neurodegeneration." (PMID 38378800, 2024). "The lack of CD68 immunoreactivity in the parenchyma of the SN or striatum at any time point suggests that the magnitude of synucleinopathy and subsequent degeneration produced in the α-syn PFF model does not trigger microglial phagocytic activity." (PMID 29716614, 2018).
thyroid tumor (3 papers, 2014 to 2025). A benign or malignant neoplasm affecting the thyroid gland. "In order to validate activation of glycolysis in TC-derived TAMs in patients with TC, formalin-fixed paraffin-embedded (FFPE) tissue sections of six thyroid tumors were immunohistochemically prepared and TAMs were stained by CD68 staining." (PMID 28123869, 2016). "When applying dichotomic assessment of immune cell numbers as low or high in thyroid tumors, we found that most TA demonstrated a low number of CD8+, CD68+ and CD163 cells." (PMID 39936166, 2025).
urothelial carcinoma (3 papers, 2021 to 2023). A malignant neoplasm derived from the transitional epithelium of the urinary tract (urinary bladder, ureter, urethra, or renal pelvis). "In patients with urothelial carcinoma IHC analysis revealed that high COX-2 expression correlated with high levels of the expression of macrophage marker CD68 and blood vessel marker CD34." (PMID 34209679, 2021). "In the similar IHC studies in samples of urothelial carcinoma overexpression of COX-2 was associated with high expression level of HIF-1a and high amount of CD68+ TAMs that promoted tumor progression and angiogenesis through TAM infiltration and hypoxia in tumor sites." (PMID 34209679, 2021).
uveal melanoma (3 papers, 2018 to 2023). A melanoma derived from melanocytes of the uveal tract. "Inflammation has been suggested to play a key role in the development of uveal melanoma with high numbers of CD68+ macrophages being associated with heavy pigmentation, microvascular density, epithelioid cells, and increased 10-year uveal melanoma-related mortality rate." (PMID 35413810, 2022). "The number of tumor-infiltrating CD68+ macrophages contributes to the prognosis in uveal melanoma." (PMID 30459241, 2018).
uveitis (3 papers, 2019 to 2022). An inflammatory process affecting a part of or the entire uvea. "In this nonhuman primate EVD model, EBOV persisted in the vitreous humor, in cells attached to the retinal inner limiting membranes, and in the ciliary body, with a predilection for CD68+ macrophage/monocytes, and with associated uveitis, retinitis, and vitritis." (PMID 31002065, 2019).
Vestibular schwannoma (3 papers, 2012 to 2021). A vestibular schwannoma (also known as acoustic neuroma, acoustic neurinoma, or acoustic neurilemoma) is a benign, usually slow-growing tumor that develops from the VIIIth cranial nerve supplying the inner ear. "Thus, a higher expression score of CD3, CD8, CD68 and CD163 was associated with larger preoperative tumor size and faster volumetric growth in vestibular schwannomas." (PMID 33530441, 2021). "The presence of CD68+ and CD45+ inflammatory cells is highly correlated with tumour proliferative activity in sporadic vestibular schwannomas." (PMID 32152754, 2020). "To further define the impact of inflammation with tumor growth in vestibular schwannoma, we performed immunohistochemical analyses of CD3, CD8, CD68 and CD163 to assess lymphocyte and macrophage infiltration in 923 tumor tissue samples of surgically resected vestibular schwannomas." (PMID 33530441, 2021).
vitamin D deficiency (3 papers, 2018 to 2022). A nutritional condition produced by a deficiency of VITAMIN D in the diet, insufficient production of vitamin D in the skin, inadequate absorption of vitamin D from the diet, or abnormal conversion of vitamin D to its bioactive metabolites. "In view of this consideration, we assume that vitamin D deficiency contributed to the extension of the active state of inflammation, maintaining a greater expression of CD68+ cells." (PMID 30370270, 2018). "Vitamin D deficiency enhanced the expressions of fibronectin, collagen IV, CD68+ and CD3+ cells in the renal cortex of VDD+Nx rats." (PMID 30370270, 2018). "By distinguishing the macrophage populations into M1 and M2, we found that vitamin D deficiency not only increased the expression of CD68+ cells (M1+M2 macrophages) but also reduced the expression of CD206+ cells (M2 macrophages)." (PMID 30370270, 2018). "Thus, our first set of data concerning CD68+ cells identified that vitamin D deficiency broadly increased the macrophage population as a whole (both M1 and M2 macrophages)." (PMID 30370270, 2018). "Of note, we found a higher renal expression of MCP-1, CD3+, and CD68+ cells in the HFDV group compared to all the other groups, demonstrating a synergistic effect of adipose tissue and vitamin D deficiency regarding the inflammatory process." (PMID 36466412, 2022). "Vitamin D deficiency increased the expression of both ECM markers, MCP1 amounts, and CD68+ and CD3+ cells expression in the renal tissue of VDD+IRI rats." (PMID 33869246, 2021).
ZIKV infection (3 papers, 2018 to 2025). "Staining of placenta tissues for macrophage subtypes via CD68 (M1) and CD163 (M2) showed both populations were present, with an increase in M1 macrophages in the villous stroma during ZIKV infection." (PMID 29343712, 2018). "A neuroinflammatory response, mainly driven by CD68/Iba+ microglia, in combination with the presence of ZIKV envelope protein, indicated that the frontal lobe for all ZIKV-infected subjects was a site of persistent ZIKV infection for a minimum of 60-day postinoculation." (PMID 35261339, 2022). "Additionally, CD68+ Hofbauer cells were present at increased density in both C2F and V2F, suggesting an inflammatory component, although not to the same extent as seen with chronic ZIKV infection in Asian-lineages." (PMID 41279781, 2025).